TNF (tumor necrosis factor)
Diseases named in the same sentence as TNF in open-access papers (continued):
Sharing a sentence is not in itself a finding about the gene and the disease.
infection (continued). "Therapeutic agents that inhibit TNF-α, a key cytokine in the host response to infection, are associated with the reactivation of latent tuberculosis." (PMID 41373747, 2025). "Some reports have described that infection-induced AM disappearance is associated with caspase-1-dependent pyroptosis and TNFα-dependent apoptosis." (PMID 40060898, 2025). "Neutrophils release proinflammatory cytokines (such as IL-6 and TNF-α), which can potentially damage lung epithelial integrity and exacerbate the risk of infection." (PMID 40270508, 2025). "The reasons for revision surgery were due to infection (40%) or other causes (60%), such as failure to fuse in the conventional DMARD group, while in the TNF-alpha inhibitor group, it was 47% for infection and 53% for other causes." (PMID 41306173, 2025). "On the other hand, pathological surges of TNF-α and IL-8 associated with infection reduce mitochondrial membrane potential, increase DNA fragmentation, inhibit sperm motility, and impair fertilization potential." (PMID 40691399, 2025). "Inflammation, oxidative stress, and pruritus exacerbate dryness, infection risk, and delayed healing, while IL‐6 and TNF‐α hinder moisture retention and protection." (PMID 40405557, 2025). "When compared to untreated mice, DEM treatment of M.tb-infected mice caused a significant increase in the levels of TNF-α at 2 weeks and 4 weeks post-infection and treatment." (PMID 40001899, 2025). "We measured the relative mRNA transcripts levels of multiple cytokines generally implicated in inflammation, namely IFNβ, IL1β and TNF in order to decipher any potential differences in the way both cell lines react to MNoV_S99 infection." (PMID 40395509, 2025). "The research highlighted that the difference in the risk of infection in the elderly who used TNF-α inhibitors between various TNF-α inhibitors, adverse events and therapeutic indications, respectively." (PMID 40371340, 2025). "The mice-adapted variant with the ΔL226/R229I mutations causes reduced levels of TNF-α in the early days post-infection in mice, which correlated with an increase in its viral titers." (PMID 40338080, 2025). "The findings of this study provide the difference in infection risk in the elderly who used TNF-α inhibitors between different TNF-α inhibitors, AEs and therapeutic indications, respectively, which provides medication suggestions for susceptible patients." (PMID 40371340, 2025). "Specifically, their study indicated that TNF inhibitors were associated with an increased risk of infections." (PMID 40546904, 2025). "Pro-inflammatory cytokines, such as TNF-α, IL-6, and IL-8, are released during inflammation caused by infection." (PMID 40278397, 2025). "A systematic review and network meta-analysis also showed that certolizumab pegol displayed the highest infection risk among five different TNF inhibitors." (PMID 40371340, 2025). "During this same phase of infection, we observed increases in the Th1 cytokines TNF and IFN-γ, which are associated with lipopolysaccharide (LPS) induction, potentially interfering with the elevation of body temperature in the mice." (PMID 39899646, 2025). "Multiple studies demonstrate a strong association between anti-TNF therapy and increased infection rates in IBD patients." (PMID 39861147, 2025). "For example, anti-TNF agents should be stopped until the infection clears, as they carry about twice the risk of serious infection compared to methotrexate, especially in the first six months of treatment." (PMID 40606458, 2025). "Tumor necrosis factor-α (TNF-α) has shown early and late upregulation in monocyte-derived DCs and primary human macrophages upon infection with the highly pathogenic H5N1 and the less pathogenic H7N9 influenza viruses, respectively." (PMID 41511331, 2025). "TLR4 deficiency markedly reduced the early (3 h post-infection) HMPV-induced TNF mRNA expression, whereas HMPV-stimulated IFNB1 mRNA expression was unaffected." (PMID 41346628, 2025).
infection (continued). "The cps mutant did not display any loss of ability to induce inflammatory response upon infection and even triggered a higher level of IL-1β and TNF-α in macrophages." (PMID 39950808, 2025). "Genes associated with TLR, TNF, and Ras signaling pathways are up-regulated up to 12 h post-infection (hpi)." (PMID 40872699, 2025). "Pathogen-induced infections generally cause rapid and massive production of various pro-inflammatory cytokines, such as TNF-α, IL-1β, IL-6, IL-12, IFN-α, IFN-β, IFN-γ, monocyte chemoattractant protein-1 (MCP-1), and IL-8." (PMID 41516024, 2025). "For example, the regulation of IL-6 production and TNF signalling were intricately linked to infection, while IL-10 was associated with reduced severity." (PMID 40643149, 2025). "The gingipain-null mutant (∆KRAB) and its parental strain (W83) caused comparable secretion of TNF-α by human neutrophils after 24 h of infection, which correlates with the viability results." (PMID 39936030, 2025). "All infections resulted in the expression of genes encoding the cytokine TNF-α, and the chemokine CCL20 in J774A.1 macrophages, with significant differences (p < 0.05) in transcription patterns compared to non-infected cells." (PMID 40727705, 2025). "Despite their therapeutic efficacy, TNF-α inhibitors are associated with profound immunosuppression, which escalates susceptibility to infections." (PMID 41329755, 2025). "Especially in countries and regions with a high prevalence of mycobacterium tuberculosis, the infection risk with TNF-α inhibitors is further increased." (PMID 40763141, 2025). "Based on real-world pharmacovigilance data, the current study systematically evaluated the association between TNF-α inhibitors and AEs of infections and infestations, providing substantial contributions to clinical practice and medication safety research." (PMID 40371340, 2025). "Here, we found significantly higher expression of the pro-inflammatory cytokines IL-6 and TNF-α in response to ST infection in cell culture supernatants of Nedd9-deficient mBMDMs measured by ELISA." (PMID 40506423, 2025). "NLRC4-deficient mice lack a crucial first line defence mechanism in IECs, resulting in accelerated infection kinetics and a rapid accumulation of pathogen-associated molecular patterns (PAMPs) that provoke broad immune responses such as TNF release." (PMID 41370284, 2025). "A linear regression analysis was performed to evaluate the association between HAdV-36 infection and levels of IL-10, IL-2, IL-6, IL-8, and TNF-α." (PMID 40284995, 2025). "Adiposopathy is associated with elevated production of proinflammatory cytokines, such as TNF-α and IL-6, which can impair wound healing, increase the risk of infection, and worsen post-operative outcomes." (PMID 40563674, 2025). "The more modest effects of ccr2 deficiency on viral loads compared with that seen after TNF blockade is explained by the unaltered presence of tissue-resident IMs before infection." (PMID 40263611, 2025). "We interpret the use of biologics, particularly TNF-α blockade, as a double-edged factor: attenuating chronic inflammation but predisposing to occult infection and impaired vascular healing, potentially contributing to pseudoaneurysm formation." (PMID 40862224, 2025). "Its peculiar mechanism of immune modulation, which avoids direct cytokine inhibition, seems to be a key factor that likely contributes to its safer profile compared to anti-TNF-α regarding the overall risk of infections and, in particular, TB reactivation." (PMID 39963138, 2025). "The results demonstrated all TNF-α inhibitors increased the risk of any infection, with certolizumab pegol displaying the highest risk." (PMID 40371340, 2025). "TNF-α re-stimulation predominantly activated pathways linked to infection and leukocyte recruitment, while IFN-γ engaged autoimmune and interferon-related pathways." (PMID 41085167, 2025).
infection (continued). "Immunosuppressive therapies, particularly tumor necrosis factor alpha (TNF-α) inhibitors such as adalimumab, predispose patients to severe infections and are associated with increased infectious morbidity and mortality." (PMID 41531628, 2025). "Elevated levels of TNF-α in serum and tissues are associated with ongoing infection, inflammation or inflammatory diseases and are responsible for the severity of their course." (PMID 40647668, 2025). "Experimental models have shown that TNF-α deficiency impairs host immune competence, increasing susceptibility to infections." (PMID 41268545, 2025). "After 24 h of macrophage cell line infection with pathogenic bacteria suspensions, the signaling cascades leading to TNF-α secretion were activated, as reflected by the high TNF-α levels." (PMID 40873569, 2025). "Earlier smaller studies have shown a higher risk of infections, hospitalizations, neoplasms, and/or mortality with anti-TNF therapy among elderly patients compared to younger ones." (PMID 39200937, 2024). "In contrast, we observed that aged mice pretreated with anti‐TNF were less susceptible to infection with decreased bacterial burdens." (PMID 38459711, 2024). "In fact, specific polymorphisms in the genes coding for some cytokines (IL-1β, IL-8, IL-10, and TNF-α) cause a more severe infection and a greater inflammatory response, as well as being associated with an increased risk of gastric cancer." (PMID 38398002, 2024). "Studies have shown that Cryptosporidium can cause the increase of TNF-α and IL-6 after infection of dairy cows, causing inflammation." (PMID 38914662, 2024). "Serum PTX3 has been identified as a potential predictor of mortality during infection and is known to be associated with TNF-α and IL-1β, which are crucial proinflammatory mediators." (PMID 39666228, 2024). "Conversely, TNF-α inhibitors increase the risk of latent TB or new infection in patients with RA, inflammatory bowel disease, or other inflammatory diseases." (PMID 37196131, 2024). "Tumor necrosis factor-alpha (TNF-⍺) inhibitors are associated with a higher risk of infection with TB." (PMID 38939259, 2024). "Since IL-10 and TNF-α represent strong virulence factors of the fungus that increase host susceptibility to infection and resistance to treatment." (PMID 38321454, 2024). "One of the core changes induced by infection is an increase in neurotoxicity caused by inflammatory products (including IL-1β and TNF-α), oxidative stress (including lipid peroxidation), and apoptosis." (PMID 39240104, 2024). "Mice treated with α-IL-1α or α-TNF-α, had partial amelioration in weight loss, which was statistically significant on days 1 and/or day 2 post infection compared to isotype controls." (PMID 39127259, 2024). "Previous studies have shown that the frequency of the tumor necrosis factor 2 (TNF2) allele with the TNF-α polymorphism was higher (12%) in patients with surgical infections in the surgical intensive care unit than in the general population." (PMID 38716051, 2024). "Although TNF-alpha inhibitors present an increased risk of infection, several researchers have been looking to quantify the risk of infection, and outweigh it with the benefit produced by the therapy." (PMID 39280117, 2024). "The protective nature of TNF against infection is also apparent in humans, as TNF polymorphisms and the use of TNF-neutralizing biologics are associated with an increased risk of infection in patients, including S. aureus." (PMID 39044282, 2024). "Several studies have shown that TNF inhibitors significantly increase the risk of serious infections and any infection." (PMID 39070789, 2024). "TNF-α GA and (GA+AA) genotypes significantly increased the risk of infection by 1.42 and 1.44-fold, respectively." (PMID 38544825, 2024).
infection (continued). "Further, the infection induces a complex immune response associated with the synthesis of interleukins IL-6, IL-1β, IL-1α, IL-2, IL-7, IL-8, tumor necrosis factor (TNF-α), interferon-γ (IFN-γ), and C-reactive protein (CRP)." (PMID 39329868, 2024). "AVH develops in response to exposure to various vascular permeabilizing factors, such as histamine, vascular endothelial growth factor (VEGF), and tumor necrosis factor-α (TNF-α), which are associated with inflammation and infection." (PMID 38675970, 2024). "In the S. Tm group, infection caused significant increases in TNF-α, IL-10, IL-22, and IFN-γ levels by 150.6%, 105.4%, 49.8%, and 103.4%, respectively, compared to the uninfected controls." (PMID 39456424, 2024). "Then, TNF-α induces aggregation of interleukin-10 and γ-interferon, which mediates an inflammatory cascade, causing fever during infection." (PMID 38656731, 2024). "Meanwhile, Th1 response with increased TNF-α and NO production was associated with the susceptibility and death of mice at nine weeks post-infection." (PMID 38392907, 2024). "For example, upon pathogenic infection but prior to tumor necrosis factor-α (TNF-α) production, WRS is rapidly secreted from monocytes without de novo synthesis; although, the mechanism of secretion is still not completely known." (PMID 39285443, 2024). "In particular, RA patients have autoimmune dysfunction, and the use of JAK inhibitors (compared with TNF-α inhibitors) will increase the risk of infection, major adverse cardiovascular events (MACE), and thrombosis in RA patients." (PMID 38378889, 2024). "Syncytial death via apoptosis, pyroptosis, or TNF-mediated necroptosis can release the pathogen-associated molecular patterns (PAMPs) and enhance excessive inflammatory responses at the site of infection." (PMID 39652608, 2024). "Mouse studies revealed that blockade of TNF signaling inhibits initial response to infection, leading to dissemination and mortality, and impairs control of existing infections, causing breakdown of granuloma and increased fungal burden." (PMID 38667927, 2024). "A challenging diagnostic circumstance then arises as some of these same drugs, such as TNF-α inhibitors, primarily act as immunosuppressants, therefore also putting patients an increased post-operative infection risk." (PMID 39045331, 2024). "Some side effects associated with TNF-alpha inhibitors are increased susceptibility to infections, like mycobacterium tuberculosis, bacterial, viral, or fungal." (PMID 39280117, 2024). "In another population-based cohort study in Korea the infection risk of JAK inhibitors versus TNF inhibitors among RA patients was compared." (PMID 38756935, 2024). "The promoter zone of the TNF-α gene is a polymorphic region, and it has been found to be associated with various inflammatory diseases and increased susceptibility to some infections." (PMID 38544825, 2024). "Despite the virus's TNF-α suppression mechanisms, this cytokine still plays a significant role in the pathogenesis of the infection, which can be associated with inflammatory response and cell apoptosis in the lungs." (PMID 40303075, 2024). "We measured the mRNA expression of TNF-α, interferon γ (IFNγ), IL-4, IL-10 and IL-12p35, which are associated with the inflammatory response during infection, in three patient groups." (PMID 38716051, 2024). "Other cytokines and chemokines in the brain were largely unaffected in TNF-deficient mice, likely due to the low expression of TNF in the brain of WT animals during craniotomy infection." (PMID 39044282, 2024). "Patients administered TNF inhibitors for immune-mediated inflammatory disorders are known to be susceptible to infection by diverse opportunistic pathogens, including Coccidioides, Histoplasma, Nontuberculous mycobacteria, and Mycobacterium tuberculosis." (PMID 39070789, 2024).
infection (continued). "Anti-Duo treated mice were protected from weight loss on day 1–2 post infection, confirming that IL-1α and TNF-α are the main drivers of early weight loss in this model." (PMID 39127259, 2024). "Both infection and stress are associated with an increased presence of inflammatory biomarkers, including tumor necrosis factor alpha and C-reactive protein." (PMID 39536047, 2024). "This increased disease severity occurs in the innate phase of the infection and is associated with increased recruitment of innate immune cells into the lungs orchestrated by IL-1α and TNF-α." (PMID 39127259, 2024). "Further linking age‐associated levels of TNF to heightened levels of these cell signaling suppressors and greater susceptibility to infection, we observed that the treatment of aged mice with anti‐TNF lowered Dusp1 expression eightfold and Ptprs by 50‐fold." (PMID 38459711, 2024). "Inhibiting TNF-alpha decreased the patient's innate immune response and made her more susceptible to infection." (PMID 39371773, 2024). "Our results add to the considerable body of evidence implicating TNF as a major determinant of aging, age‐related macrophage dysfunction, and increased susceptibility to infection." (PMID 38459711, 2024). "The TNF signaling pathway is associated with the upregulation of cytokines and chemokines, which are essential for recruiting immune cells to the site of infection." (PMID 39682481, 2024). "As M. tuberculosis infection causes chronic inflammation, infected mice showed increased TNF-α and IL-6 levels in the lung after 52 weeks of infection." (PMID 38958367, 2024). "In this study, we evaluated of the infection risk among patients with inflammatory arthritis receiving treatment with five different TNF inhibitors." (PMID 39070789, 2024). "This infection is associated with the production of cytokines like the IL family, TNF-α, transforming growth factor-β, and chemokines, which trigger neurodegenerative disease." (PMID 39516514, 2024). "Bronchiectasis and the use of immunosuppressants, especially TNFα blockers, have been associated with an increased risk of infection." (PMID 38256476, 2024). "The results demonstrated all TNF inhibitors increased the risk of any infection, with certolizumab pegol displaying the highest risk." (PMID 39070789, 2024). "IL-6 is a pleotropic cytokine typically released in the context of infection and tissue damage induced by toll-like receptors (TLRs) and damage-associated molecular proteins (DAMPs), often in association with IL-1β and TNFα." (PMID 39595087, 2024). "The increase of infection related indexes, for example, serum levels of IL-1β, TNF-α, and IL-6, were significantly associated with a blood glucose rise." (PMID 38570745, 2024). "We consider the difference in infection risk for TNF inhibitors to be mostly explained by their different molecular structures, leading to differences in pharmacokinetics and mechanisms of action." (PMID 39070789, 2024). "The higher infection risk observed in some studies in the elderly population treated with the anti-TNF-α antibodies should probably be of special concern and the awareness of its presence in this group of patients should be heightened." (PMID 38792308, 2024). "While type-1 T-cells induce IL-6, IL-1β, TNF-α, and IL-12 production by monocytes/macrophages to fight the infection, type-2 T-cells are associated with a regulatory phenotype (IL-10 and TGF-β) and successful infection establishment." (PMID 39192975, 2024). "Although other systematic reviews have measured the risk of malignancies and serious infections among patients treated with anti-TNF-α, most have focused exclusively on RCTs." (PMID 39064585, 2024). "This suggests that the use of TNFα blockers, together with more corticosteroids and cytotoxic drugs in the second group, increased the risk of infection compared to the use of TNFα blockers alone, which were more frequently used in the first group." (PMID 38256476, 2024).